VDR (vitamin D receptor)
Diseases named in the same sentence as VDR in open-access papers (continued):
Sharing a sentence is not in itself a finding about the gene and the disease.
breast cancer (248 papers, 2001 to 2025). A primary or metastatic malignant neoplasm involving the breast. "Further studies are needed to explore the diagnostic, prognostic, and therapeutic implications of VDR in breast cancer." (PMID 40898467, 2025). "The findings suggest a strong association between VDR and ER, PR status, and the Ki-67 proliferation index in breast carcinoma." (PMID 40898467, 2025). "The main findings of this study were significant associations between positive VDR staining of the nuclear membrane in breast cancer with favorable tumor characteristics and a longer BCFI and OS." (PMID 38612962, 2024). "The main finding of this study was that certain germline VDR genotypes were associated with breast cancer prognosis." (PMID 38351438, 2024). "Several studies have investigated the associations between VDR in breast cancer tissue and breast cancer prognosis and found VDR to be associated with favorable outcomes." (PMID 38612962, 2024). "In conclusion, positive VDR staining in the nuclear membranes of invasive breast cancer cells was associated with an improved breast cancer prognosis." (PMID 38612962, 2024). "The aim of this study was to investigate the associations between four VDR SNPs (Taq1, Tru91, Bsm1, and Fok1) and breast cancer prognosis." (PMID 38351438, 2024). "The present investigation centers on elucidating the prevalence and distribution patterns of VDR Bsm1 and Apa1 polymorphisms among breast cancer patients in Isfahan, comparing these profiles with those observed in healthy population cohorts." (PMID 38440355, 2024). "The primary aim was to validate previous research that has suggested a positive association between the presence of nuclear VDR and breast cancer prognosis." (PMID 38612962, 2024). "Recent investigations have predominantly focused on elucidating the link between VDR polymorphisms and cancer risk, spanning various malignancies including skin, colon, ovarian, bladder, prostate, and breast cancers." (PMID 38440355, 2024). "This study further confirms the results of several previous studies, demonstrating that VDR expression in breast cancer tissue is inversely associated with disease aggressiveness." (PMID 38612962, 2024). "Tumor-specific positive nuclear membrane VDR(num) staining was associated with favorable tumor characteristics and a longer breast cancer free interval (BCFI; HR: 0.64; 95% CI: 0.44–0.95) and overall survival (OS; HR: 0.52; 95% CI: 0.34–0.78)." (PMID 38612962, 2024). "Previous research has indicated an association between the presence of the vitamin D receptor (VDR) in breast cancer tissue and a favorable prognosis." (PMID 38612962, 2024). "The aim was to investigate associations between four previously studied VDR SNPs (Taq1, Tru91, Bsm1, and Fok1) and prognosis in different groups of breast cancer patients." (PMID 38351438, 2024). "Vitamin D receptor (VDR) genes have recently been exposed and implicated in the development of breast cancer." (PMID 37701195, 2023). "In connection to this, it is important to mention that high serum levels of vitamin D and high expression of the vitamin D receptor are linked to better prognosis in breast cancer." (PMID 36980716, 2023). "The study found that VDR deficiency led to gut dysbiosis, increasing susceptibility to breast cancer induced by DMBA." (PMID 37539732, 2023). "Due to the plethora of preclinical findings that demonstrate a role for VDR in breast cancer formation and growth, several clinical trials have investigated the preventative effect of vitamin D supplementation on breast cancer risk." (PMID 37583424, 2023). "Despite not being the focus of this study, women with lower serum levels of 25-hydroxyvitamin D and higher tissue levels of VDR and tissue expression of the estrogen receptor gene had a significantly higher risk of breast cancer incidence." (PMID 37630755, 2023). "Low vitamin D status and VDR genetic polymorphisms are associated with an increased risk of breast cancer in Ethiopian women." (PMID 37886170, 2023).
breast cancer (continued). "The VDR is expressed in breast cells, and a meta-analysis found that higher levels of VDR in the nucleus and cytoplasm of breast cancer cells were significantly associated with a better overall survival among breast cancer patients." (PMID 36014928, 2022). "High VDR expression was associated with improved prognosis and decreased mortality from breast cancer." (PMID 35743729, 2022). "This study aimed to study associations between pre-diagnostic systemic levels of vitamin D and expression of VDR in subsequent breast tumors, and interactions between vitamin D and VDR on breast cancer mortality." (PMID 36014861, 2022). "Numerous studies have highlighted that high expression levels of VDR in breast cancer tissues are associated with favorable tumor‐related prognostic factors and a decreased risk of breast cancer death." (PMID 34003583, 2022). "Another aim of this study was to analyze if the association between VDR expression and breast cancer mortality in any way was affected by pre-diagnostic vitamin D levels." (PMID 36014861, 2022). "Previously, we reported that the loss of the VDR promotes an epithelial to mesenchymal transition, which increased cell invasiveness and metastasis to bone in a murine model of breast cancer metastasis to bone." (PMID 36362766, 2022). "In clinical studies of primary cancers, a low VDR expression was associated with metastases in colon, urothelial and breast cancers." (PMID 36362766, 2022). "High nuclear VDR expression within tumor cells was associated with favorable prognostic factors and a decreased risk of breast cancer death." (PMID 33917614, 2021). "Wang and colleagues have reported that VDR TaqI polymorphism is related to an increased risk of breast cancer, especially among Caucasian populations." (PMID 33732250, 2021). "We determined how vitamin D receptor (VDR) is linked to disease outcome in estrogen receptor-positive (ER+) breast cancer patients treated with tamoxifen (TAM)." (PMID 34069442, 2021). "One study showed that PTPH1 binds to the vitamin D receptor (VDR) in the cytosol of breast cancer cells, which causes accumulation of VDR in the cytosol that leads to reduced nuclear localization and transcription." (PMID 34884670, 2021). "Other studies have shown the importance of the VDR for protecting against tumor development, such as development of breast cancer in VDR deficient mice and in response to UV irradiation." (PMID 34206371, 2021). "Several previous studies have reported the association between polymorphisms in VDR SNPs and risk of cancer, such as breast cancer and its survivors, colorectal cancer, lung cancer, advanced gallbladder cancer, bladder cancer, gastric cancer and oral cancer." (PMID 34006324, 2021). "Meta-analysis studies on the association between VDR polymorphisms and breast cancer risk are inconsistent." (PMID 34727991, 2021). "TCGA data indicate that breast cancers rarely display mutations or altered levels of expression of the VDR gene." (PMID 34950835, 2021). "This study will aim to investigate the possible effects of individual polymorphisms in vitamin D receptor (VDR) as well as effects of VDR haplotypes on response to vitamin D supplementation in breast cancer survivors." (PMID 34727991, 2021). "Presence of VDR in normal breast epithelial cells and breast cancer cells suggests a relation between it and breast cancer risk." (PMID 33906311, 2021). "In this study we assessed the association of a comprehensive set of SNPs of VDR and GC genes and breast cancer prognosis in a cohort of 368 breast cancer patients with a positive family history of cancer but wild type for BRCA1 and BRCA2." (PMID 33917614, 2021). "From the present study as high VDR is good prognostic factor for breast carcinoma as it associated with low tumor and nodal stage together with low grade, absent vascular invasion and metastasis." (PMID 33906311, 2021).
breast cancer (continued). "In conclusion, our case-control study shows that TaqI and ApaI polymorphisms of the VDR gene are associated with breast cancer risk." (PMID 32986367, 2020). "We focused on the distribution of VDR ApaI and TaqI single nucleotide polymorphisms (SNPs) in Isfahan province breast cancer patients compared to a healthy population." (PMID 32986367, 2020). "This study aimed to investigate the association of ApaI and TaqI polymorphisms of the VDR gene with breast cancer risk which followed by stratified analysis." (PMID 32986367, 2020). "Vitamin D deficiency and the low tumor expression level of VDR are correlated with aggressive breast cancer characteristic." (PMID 32257539, 2020). "In the current study, we investigated the association of ApaI and TaqI polymorphisms in the VDR gene with breast cancer in a case-control study and a stratified analysis." (PMID 32986367, 2020). "The association between expression of this lncRNA and VDR has been assessed in breast cancer tissues." (PMID 32514489, 2020). "They reported increased odds of breast cancer in women with a polymorphism in VDR and an additive effect of low 25(OH)D on odds of breast cancer." (PMID 32218376, 2020). "An epidemiological study examined the risk of breast cancer related to polymorphism of VDR gens and 25 (OH)D in plasma." (PMID 31350967, 2019). "This study examine the impact of oral high-dose vitamin D3 supplementation on circulating inflammatory markers and TAC according to four VDR polymorphisms (i.e. BsmI, ApaI, TaqI, and FokI) in women with breast cancer." (PMID 31350967, 2019). "In breast cancer cell lines, vitamin D signaling inhibits expression of a tumor progression gene (Id1), and ablation of VDR expression causes increased tumor growth and development of metastases." (PMID 31252594, 2019). "The present study indicates that high VDR expression in breast cancer cell nuclei is associated with favorable prognostic factors and a decreased risk of breast cancer death." (PMID 31358030, 2019). "This study was aimed to assess the impact of vitamin D3 supplementation on the serum concentration of inflammatory markers and antioxidant capacity with regard to VDR polymorphism in the VDR gene in breast cancer women." (PMID 31350967, 2019). "The VDR polymorphisms have been extensively explored in breast cancer risk assessment studies and their possible significance in breast cancer has been inconclusive." (PMID 30699973, 2019). "There was a statistically significant association between VDR expression and BCM within the Luminal B-like tumors as nuclear VDR positivity was associated with a decreased risk of breast cancer death (0.37, 0.18–0.77)." (PMID 31358030, 2019). "To summarize, this is the first work studying the association of the VDR SNPs and haplotypes with metabolic status and obesity indices in response to vitamin D3 supplementation among breast cancer survivors." (PMID 31395070, 2019). "The FokI FF allele together with other VDR polymorphisms has been shown to amplify breast cancer risk in a Caucasian population." (PMID 30699973, 2019). "Covariation between VDR expression and established prognostic factors for breast cancer was analyzed, as well as associations between VDR expression and breast cancer mortality." (PMID 31358030, 2019). "We have observed that carriers of the VDR FokI GG (FF) genotype (OR = 1.44, 95% CI 1.01–2.05) were associated with risk of breast cancer." (PMID 30699973, 2019). "As VDR expression covaried with prognostic factors, it was expected to find associations also with the suggested breast cancer treatment." (PMID 31358030, 2019). "Both crude and adjusted analyses showed a statistically significant association between nuclear VDR positivity (a fraction above 10% of stained nuclei) and a low risk of breast cancer-associated death (HR = 0.56, 0.34–0.91) adjusted analysis)." (PMID 31358030, 2019).
breast cancer (continued). "In contrast to our finding, the VDR-FokI f allele has been associated with increased risk of breast cancer in Canadians and African Americans." (PMID 30699973, 2019). "Despite the epidemiological evidence, there are no published trials regarding the effects of vitamin D supplementation on blood levels of 25 (OH)D, TNF-α, TGF-β1, and TAC in accordance with the different variation of VDR polymorphism among breast cancer women." (PMID 31350967, 2019). "This corresponds to the finding that VDR-positive tumors were found to be associated with a decreased risk of breast cancer-specific mortality, but this association was also independent of other prognostic factors." (PMID 31358030, 2019). "This study found that high expression of VDR in invasive breast tumors is associated with favorable prognostic factors and a low risk of breast cancer death." (PMID 31358030, 2019). "We found that changes in WC and circulating LDL-C were associated with the VDR ApaI SNPs whereas changes in muscle mass were associated with the BsmI SNPs in breast cancer survivors supplemented with vitamin D3." (PMID 31395070, 2019). "Vitamin D exerts its functions through the vitamin D receptor (VDR), and the aim of the current study was to investigate if the expression of VDR in invasive breast tumors is associated with breast cancer prognosis." (PMID 31358030, 2019). "Their results are also in line with ours, suggesting that VDR expression is associated with a better breast cancer prognosis." (PMID 31358030, 2019). "Four types of VDR polymorphisms consisting FokI, BsmI, ApaI, and TaqI have more association with breast cancer." (PMID 31350967, 2019). "Previous studies on vitamin D-associated SNPs and breast cancer risk have been focused mainly on genetic variants of the vitamin D receptor, and a few studies have been done on GC, which is the gene encoding DBP." (PMID 29291743, 2018). "CpG island methylation in the VDR promoter region was associated with reduced expression of VDR in colon and breast cancer cells." (PMID 29657326, 2018). "Researchers investigating vitamin D-related SNPs and breast cancer risk have focused mainly on SNPs located in the vitamin D receptor (VDR) gene." (PMID 29291743, 2018). "Despite the expression of VDR in breast cancer cells, vitamin D deficiency is very common in patients with breast cancer." (PMID 30037009, 2018). "Only one was directly associated with breast cancer risk (cg10592901 in VDR, HR = 1.04, 95% confidence interval (CI) 1.01–1.07)." (PMID 29996894, 2018). "Further, polymorphisms in VDR have been demonstrated to be associated with breast cancer risk and both RXR and PPARγ have been demonstrated to comprise anti-cancer cell activity." (PMID 28427429, 2017). "The discovered interactions implicated the glutathione conjugation, vitamin D receptor, purine metabolism, mitotic prometaphase, and steroid hormone biosynthesis pathways as major modifiers of breast cancer risk." (PMID 28957314, 2017). "Our previous studies in VDR SNPs from the same cohort of African-American and Hispanic women showed that specific VDR gene polymorphism was associated with breast cancer in African-Americans and predict DFS only." (PMID 29064397, 2017). "Further studies will be needed in order to clarify the mechanisms underlying the protein degradation of KCa1.1 via VDR signaling pathways in breast cancer cells." (PMID 27973439, 2016). "A recent meta-analysis of high-quality studies demonstrated that the Fok1 polymorphism of the VDR gene was closely associated with breast cancer risk." (PMID 26985904, 2016). "For example, a study investigating VDR TaqI and BsmI alleles and the genotype frequencies in female breast cancer patients showed similar results to their control group." (PMID 27688524, 2016). "Several recent studies (case-control studies and nested case-control studies) investigated the association between VDR polymorphism and breast cancer risk." (PMID 27149457, 2016).
breast cancer (continued). "Of these 205 abstracts, we identified 51 potentially relevant studies that described the association between the VDR gene polymorphism and breast cancer risk after screening the titles and abstracts." (PMID 27149457, 2016). "The current investigation examines the association between VDR-Cdx2 polymorphism and breast cancer in premenopausal females from Southern Pakistan." (PMID 25799416, 2015). "Vitamin D is postulated to decrease the risk of breast cancer by inhibiting cell proliferation via the vitamin D receptor (VDR)." (PMID 26517870, 2015). "It has recently been shown that VDR signaling inhibits epithelial to mesenchymal transition and the metastatic potential of human and mouse breast cancer cells induced by tumor associated macrophages in vitro and in an orthotopic model of breast cancer." (PMID 26008979, 2015). "Herein, we examined mammary tumor onset and progression using a Ron-driven murine model of breast tumorigenesis crossed with VDR deficient mice." (PMID 26008979, 2015). "In summary, our clinical findings revealed a close association between specific VDR Cdx2 polymorphism and breast cancer bearing more aggressive phenotype." (PMID 25849303, 2015). "The objective of this study is to assess the relationship between the Cdx2 VDR polymorphism and the activities of VDR in human breast cancer cell lines and carcinomas breast patients." (PMID 25849303, 2015). "VDR gene polymorphisms have been identified and analyzed so far in a wide variety of diseases, including Parkinson disease, cancer of the breast, and autoimmune diseases." (PMID 25649962, 2015). "Pearson chi square test was used to assess the association between VDR-Cdx2 genotype and breast cancer while genotype distribution in controls was evaluated by Hardy-Weinberg equilibrium (HWE)." (PMID 25799416, 2015). "Two common single nucleotide polymorphisms (SNPs) in the VDR gene, rs1544410 (BsmI) and rs2228570 (FokI), are inconsistently associated with breast cancer risk in Caucasian populations, while data for Asians are scarce." (PMID 26517870, 2015). "Several studies have been carried out to evaluate the relationship between VDR gene polymorphisms and breast cancer risk." (PMID 25799416, 2015). "Further investigations examining additional single nucleotide polymorphisms (SNPs) in VDR are required to assess their relationships with breast cancer." (PMID 25799416, 2015). "We also did not measure vitamin D serum levels to examine interactions between vitamin D levels and VDR SNPs in relation to breast cancer risk." (PMID 26517870, 2015). "Among all VDR polymorphisms limited data is available on VDR-Cdx2 polymorphism and breast cancer susceptibility." (PMID 25799416, 2015). "Others have also highlighted Fok1 SNP as the most notorious polymorphism of VDR gene influencing breast cancer susceptibility." (PMID 25799416, 2015). "Treatment with DAC restored expression of the active transcript variant of VDR in breast cancer cell lines, indicating promoter methylation as cause of truncated protein expression." (PMID 24808866, 2014). "One possible explanation for the unique association of vitamin D with breast cancer risk among white women is a potential modifying effect of this association by vitamin D receptor polymorphisms (FokI, BgII) that vary substantially by ethnic group." (PMID 24438060, 2014). "A meta-analysis of high-quality studies demonstrated that the Fok1 polymorphism of the VDR gene was closely associated with breast cancer risk." (PMID 24769568, 2014). "A meta-analysis of high-quality studies showed that the Fok1 polymorphism of the VDR gene was associated with an increased risk of breast cancer (ff vs. Ff+FF, OR: 1.09, 95%CI: 1.02 to 1.16, p = 0.007)." (PMID 24769568, 2014). "According to the criteria eligibility, 39 studies was identified regarding the associations between the Fok1, poly-A, Bsm1, Taq1 or Apa1 polymorphisms of VDR gene and breast cancer risk." (PMID 24769568, 2014).